CCDC40 (coiled-coil domain 40 molecular ruler complex subunit)
Description:
Required for assembly of dynein regulatory complex (DRC) and inner dynein arm (IDA) complexes, which are responsible for ciliary beat regulation, thereby playing a central role in motility in cilia and flagella. Probably acts together with CCDC39 to form a molecular ruler that determines the 96 nanometer (nm) repeat length and arrangements of components in cilia and flagella (By similarity). Not required for outer dynein arm complexes assembly. Required for axonemal recruitment of CCDC39.
Synonyms: KIAA1640; FLJ20753; FLJ32021; CILD15; FAP172; CFAP172
Tractability: Small molecule: a structure with a bound ligand is known. Antibody: its Gene Ontology location is reachable by antibodies, with medium confidence. PROTAC: ubiquitination databases record sites on it.
Gene: Protein-coding gene on chromosome 17 (80,036,632 to 80,100,613, forward strand). Ensembl gene ENSG00000141519.
Subcellular location: Cytoplasm; Cell projection, cilium
Subcellular location (Human Protein Atlas): Cytosol; Microtubules; Primary cilium; Cytokinetic bridge; Mid piece
Gene Ontology:
Biological process: axonemal dynein complex assembly; cilium movement; determination of digestive tract left/right asymmetry; determination of liver left/right asymmetry; determination of pancreatic left/right asymmetry; epithelial cilium movement involved in determination of left/right asymmetry; epithelial cilium movement involved in extracellular fluid movement; flagellated sperm motility; heart looping; inner dynein arm assembly; lung development; motile cilium assembly; regulation of cilium beat frequency; axoneme assembly; cilium organization; protein localization to cilium
Cellular component: axoneme; cilium; motile cilium; cytoplasm; extracellular region
Genetic constraint (gnomAD): Loss-of-function variants: 102 observed, 125.05 expected, observed/expected ratio (o/e) 0.82, 90% interval 0.69 to 0.96. The upper end of that interval is the gene's LOEUF score, 0.96, which puts it in group 4 of 6, group 1 being the genes least tolerant of losing a copy. Missense variants: 1,437 observed, 1,534.8 expected, observed/expected ratio (o/e) 0.94, 90% interval 0.9 to 0.98. Synonymous variants: 570 observed, 617.32 expected, observed/expected ratio (o/e) 0.92, 90% interval 0.86 to 0.99.
Gene-disease validity (ClinGen):
ClinGen rates the evidence that CCDC40 causes each of these diseases.
primary ciliary dyskinesia 15 (autosomal recessive): Definitive.
Homologues: Orthologues: chimpanzee CCDC40 (98% identical), dog CCDC40 (68% identical), guinea pig CCDC40 (64% identical), rat Ccdc40 (61% identical), pig CCDC40 (60% identical), mouse Ccdc40 (53% identical), zebrafish ccdc40 (30% identical), Drosophila melanogaster l(2)41Ab (18% identical).
Diseases named in the same sentence as CCDC40 in open-access papers:
CCDC40 is named in the same sentence as 28 diseases in open-access papers, as found by Europe PMC text mining. Sharing a sentence is not in itself a finding about the gene and the disease. The quoted sentences say what the papers report.
primary ciliary dyskinesia (23 papers, 2012 to 2026). A rare, genetically heterogeneous, primarily respiratory disorder characterized by chronic upper and lower respiratory tract disease. "Mutations in CCDC39 (e.g. c.1072del) and CCDC40 (e.g. c.901C>T) destabilize the radial spoke structure, leading to axonemal disorganization and loss of motility, as observed in primary ciliary dyskinesia (PCD)." (PMID 40847540, 2026). "Biallelic mutations of CCDC39 and CCDC40 have been found in patients with ‘radial spoke defects’ in primary ciliary dyskinesia." (PMID 37601242, 2023). "Our findings extend the mutation spectrum of CCDC40 gene related Kartagener's syndrome, which is very important for gene diagnosis of the disease." (PMID 35433722, 2022). "As an example, DNAH11, DNAH5, DNAI1, and CCDC40 genes have been linked to primary ciliary dyskinesia." (PMID 33574797, 2020). "CCDC40 (Coiled-Coil Domain Containing 40) mapping on the chromosome 17q25.3, is another gene associated with ciliary dyskinesia." (PMID 33574797, 2020). "CCDC39 and CCDC40 were first identified as causative mutations in primary ciliary dyskinesia patients; cilia from patients show disorganized microtubules, and they are missing both N-DRC and inner dynein arms proteins." (PMID 26348919, 2015). "Ccdc40 is essential for left-right patterning in both mice and humans, full range cilia motility and a causal mutation for a variant of primary ciliary dyskinesia in humans." (PMID 22479196, 2012). "Aberrant function of CCDC40 has been reported to cause primary ciliary dyskinesia." (PMID 34689164, 2021). "Mutations in CCDC40 were recently found in patients with Primary Ciliary Dyskinesia." (PMID 23171430, 2012). "Disease-causing bi-allelic DNA variants in CCDC39 and CCDC40 are frequent causes of the hereditary disorder of primary ciliary dyskinesia (PCD)." (PMID 39056782, 2024). "The diagnostic genetic variant rate identified using WES was 11.1% (8/72), in which primary ciliary dyskinesia (PCD)-associated gene mutations (CCDC40, CCDC114, DNAH5, DNAH11, and ARMC4) accounted for the vast majority (n = 5)." (PMID 35518361, 2022). "The key roles of CCDC39 and CCDC40, which are involved in axonemal disorganization and inner dynein arm loss, in patients with primary ciliary dyskinesia (PCD) have been demonstrated previously." (PMID 34508138, 2021). "In this regard, we observed situs inversus totalis (Kartagener syndrome) in two patients with VUS in CCDC40 and DNAI1 and female infertility in another patient with VUS in CCDC40, as previously reported by others." (PMID 37998386, 2023). "Such structural alterations are also observed in the cilia of patients with PCD (primary ciliary dyskinesia) who have mutations in CCDC39 and CCDC40, the human orthologs of FAP59 and FAP172, respectively." (PMID 31319499, 2019). "Importantly, high speed video microscopy analysis of respiratory cilia from nasal brush biopsies obtained from Primary Ciliary Dyskinesia (PCD) patients with CCDC40 mutations demonstrate abnormal beat patterns and rigid appearance." (PMID 28182636, 2017). "Among 32 genes in which defects lead to primary ciliary dyskinesia, six (Dnaic2, Ccdc40, Armc4, Ccdc164/DRC1, Rsph9, Ccdc11) are strongly downregulated in Rfx2-/- testes at both time points, and three others only at P30 (Ccdc65, Zmynd10, Ccno)." (PMID 26162102, 2015). "The CCDC40 mutation is best known as the major cause of primary ciliary dyskinesia, but its association with cancer has not yet been reported." (PMID 37121965, 2023). "Importantly, CCDC40 deficiency causes primary ciliary dyskinesia (PCD)." (PMID 35804605, 2022). "The mutations in CCDC39 and CCDC40 are the major cause of primary ciliary dyskinesia with axonemal disorganization and absent inner dynein arms." (PMID 35233959, 2022).
primary ciliary dyskinesia (continued). "CCDC40, a coiled-coil protein whose transcript levels are increased in both P25-Shank3 and P60-Shank3 transcripts, is known to regulate motile cilia function and left-right axis formation with implications in the primary ciliary dyskinesia." (PMID 36311023, 2022). "One patient with VUS in CCDC40 and DNAI1 had Kartagener syndrome, respectively, and one patient with VUS in CCDC40 had a history of congenital heart but no laterality defect." (PMID 37998386, 2023).
male infertility (7 papers, 2020 to 2025). The inability of the male to effect fertilization of an ovum after a specified period of unprotected intercourse. "Mutations within the CCDC40 are associated with cilia and sperm dysmotility, and are suspected to be involved in idiopathic male infertility." (PMID 35887003, 2022). "Therefore, we hypothesize that the significant downregulation of DEGs (CFAP70, TTC29, CCDC40, DNAAF4, SYCE3, STK36, SPI1 and EMX2) in hybrid yellow catfish is the primary cause of male infertility or reduced fertility." (PMID 38891632, 2024). "Mutations in CCDC39, CCDC40, and CCDC103 presented cilia axonemal disorganization, absent inner dynein arms, and male infertility." (PMID 35955660, 2022).
Ciliopathies (4 papers, 2020 to 2023). "For example, ciliopathy patients with variants in CCDC39 or CCDC40 genes display severe derangement of the axoneme and especially poor patient outcomes, because the CCDC39 / CCDC40 complex is the “ruler” that sets the length for the repeating units of ODAs and IDAs12." (PMID 37781579, 2023).
Infertility (4 papers, 2021 to 2025). "We report 2 novel mutations in CCDC40 gene (c.1259delA and EX17_20 deletion) resulted in immobility of sperm and infertility of the proband." (PMID 34941110, 2021). "CCDC40 were proposed as a likely gene to cause infertility; thus, the mRNA expression reduction here observed in this may also contribute to the infertility of our proband." (PMID 36856967, 2023). "Among women with known genetic results, those with infertility had DNAH5, DNAAF3, ZMYND10, CCDC40, RSPH9 and HYDIN mutations." (PMID 40142748, 2025). "We identified ten infertile male individuals with pathogenic variants in CCDC39 (one) and CCDC40 (two) encoding ruler proteins, RSPH1 (two) and RSPH9 (one) encoding radial spoke head proteins, and HYDIN (two) and SPEF2 (two) encoding CP-associated proteins, respectively." (PMID 36873931, 2023).
situs inversus (4 papers, 2017 to 2021). A congenital condition in which there is complete right-to-left reversal of the position of the major thoracic and abdominal organs (that is, they are arranged in a mirror image of the normal positioning). "Human patients as well as zebrafish mutants and morphants with mutations in CCDC40 show situs inversus and heterotaxia." (PMID 28182636, 2017). "Nevertheless, these variants are very likely to lead to a disrupted CCDC40 protein, and consequently to dysfunction of the CCDC39-CCDC40 complex, which possibly justifies the observed axoneme patterns and the situs inversus totalis." (PMID 31443223, 2019). "Malfunction of Ccdc40 in mice resulted in left pulmonary isomerism and lung situs inversus." (PMID 33488611, 2020).
bronchiectasis (2 papers, 2022 to 2023). Segmental, irreversible dilation of the bronchial tree resulting in the accumulation of secretions which leads to obstruction. "In our study, both individuals with CCDC40 pathogenic variants had IDA defects along with axoneme disorganization, chronic rhinosinusitis, bronchiectasis, and recurrent pneumonia, and one of them also presented dextrocardia." (PMID 35886035, 2022). "Consistent with previous studies in individuals with defects of the axonemal ruler CCDC40-mutant individual OP-11 II2 presented with situs inversus totalis and bronchiectasis." (PMID 36873931, 2023).
Lung disease (2 papers, 2020 to 2022). "Lung disease and lung function are reportedly worse in those with inner dynein arm and central apparatus defects with microtubular disorganization ultrastructural defects, most of whom have biallelic mutations in CCDC39 or CCDC40." (PMID 31960620, 2020).
Neonatal respiratory distress (2 papers, 2021 to 2022). Respiratory difficulty as newborn. "In addition, another study has shown that patients with PCD and mutations in CCDC40 have a more severe disease course with an earlier onset and a higher prevalence of neonatal respiratory distress than PCD patients without such mutations." (PMID 35518361, 2022).
congenital heart disease (1 paper, 2021). A heart disease that is present at birth. "Furthermore, CCDC40 has been shown to be essential for left-right axis formation in tissue development, which may be related to congenital heart disease." (PMID 34689164, 2021).
cystic fibrosis (1 paper, 2015). Autosomal recessive disorder caused by pathogenic variants in the CFTR gene (cystic fibrosis transmembrane conductance regulator), which encodes a chloride and bicarbonate channel expressed in epithelial cells, and follow the diagnosis criteria. "Unexpectedly, the long-term prognosis of children with CCDC39 or CCDC40 mutations is worse than for other PCD patients, and similar to patients with cystic fibrosis." (PMID 26348919, 2015).
endometritis (1 paper, 2022). An acute or chronic, usually bacterial infectious process affecting the endometrium. "Moreover, co-expression and interactions between lncRNAs and the CCDC40 and ZMYND10 are involved in bovine endometritis." (PMID 35887003, 2022).
esophagus disorders (1 paper, 2020). "Gene-wide CCDC40 variants have also been associated with myeloid leukemia death (P = 1.7 × 10−8) and self-reported esophagus disorders (P = 1.8 × 10−9) in UK Biobank39." (PMID 32371927, 2020).
Joubert syndrome (1 paper, 2021). Joubert syndrome (JS) is characterized by congenital malformation of the brainstem and agenesis or hypoplasia of the cerebellar vermis leading to an abnormal respiratory pattern, nystagmus, hypotonia, ataxia, and delay in achieving motor milestones. "The remaining novel variants were: CCDC39:p.Glu598* (CADD, 37); CCDC40:c.1097delT (frameshift); CEP104:p.Glu698Lys (Joubert syndrome 25, Patient 9); DNAAF5:p.Val431Ala (Condel: 0.886); DNAH5 duplication of exon 1–48 (unknown significance); HYDIN:p.Pro3213Arg (likely pathogenic, Patients 17–18)." (PMID 34768622, 2021).
Tumor (2 papers, 2019 to 2021). "This the first demonstration that this axis functions as a tumor-related regulatory pathway, which provides insight into additional functions of CCDC40." (PMID 34689164, 2021). "KTN1 knockdown increases the expression of CCDC40, PSMA1, and ADRM1 to mediate tumor suppressor functions in vivo and in vitro." (PMID 34689164, 2021).
CCDC40 also shares sentences with these, for which no sentence is quoted: Kartagener Syndrome (2 papers); pulmonary hypertension (2); Situs inversus totalis (2); asthma (1); cancer (1); chronic rhinosinusitis (1); female infertility (1); gallstones (1); Hydrocephalus (1); immune disease (1); infection (1); myeloid leukemia (1); recurrent pneumonia (1); respiratory diseases (1).